HOXD1 (homeobox D1)
Description:
Sequence-specific transcription factor which is part of a developmental regulatory system that provides cells with specific positional identities on the anterior-posterior axis. Acts on the anterior body structures.
Synonyms: HOX4; HOX4G; Hox-4.7
Tractability: No criterion of Open Targets' tractability assessment is met for any kind of drug.
Gene: Protein-coding gene on chromosome 2 (176,188,667 to 176,190,907, forward strand). Ensembl gene ENSG00000128645.
Subcellular location: Nucleus
Subcellular location (Human Protein Atlas): Nucleoplasm
Pathways (Reactome):
Developmental Biology: Activation of anterior HOX genes in hindbrain development during early embryogenesis
Gene Ontology:
Molecular function: sequence-specific double-stranded DNA binding; DNA-binding transcription factor activity, RNA polymerase II-specific; RNA polymerase II cis-regulatory region sequence-specific DNA binding; DNA binding; DNA-binding transcription factor activity; sequence-specific DNA binding
Biological process: regulation of transcription by RNA polymerase II; regulation of DNA-templated transcription
Cellular component: nucleoplasm; chromatin; nucleus
Genetic constraint (gnomAD): Loss-of-function variants: 17 observed, 18.49 expected, observed/expected ratio (o/e) 0.92, 90% interval 0.63 to 1.38. The upper end of that interval is the gene's LOEUF score, 1.38, which puts it in group 5 of 6, group 1 being the genes least tolerant of losing a copy. Missense variants: 500 observed, 406.95 expected, observed/expected ratio (o/e) 1.23, 90% interval 1.14 to 1.32. Synonymous variants: 239 observed, 195.74 expected, observed/expected ratio (o/e) 1.22, 90% interval 1.1 to 1.36.
Homologues: Orthologues: chimpanzee HOXD1 (99% identical), macaque HOXD1 (93% identical), pig HOXD1 (83% identical), rabbit HOXD1 (83% identical), mouse Hoxd1 (82% identical), rat Hoxd1 (82% identical), dog HOXD1 (75% identical), guinea pig HOXD1 (73% identical), tropical clawed frog hoxd1 (47% identical). Paralogues in human: HOXA1 (37% identical), HOXB1 (31% identical), HOXA4 (20% identical), HOXB5 (20% identical), HOXB3 (20% identical), HOXB2 (19% identical), HOXC4 (19% identical), HOXD4 (19% identical), HOXD3 (19% identical), HOXA2 (19% identical), HOXA3 (19% identical), HOXA5 (18% identical), and 30 more.
Diseases named in the same sentence as HOXD1 in open-access papers:
HOXD1 is named in the same sentence as 25 diseases in open-access papers, as found by Europe PMC text mining. Sharing a sentence is not in itself a finding about the gene and the disease. The quoted sentences say what the papers report.
breast carcinoma (6 papers, 2016 to 2023). "HOXD1 has been validated as a biomarker for diagnosis and prognosis of breast cancer via a functional hypermethylome screen, while HOXD10, as a direct target of miR-10b, suppresses cell migration and invasion in various types of cancer." (PMID 26985770, 2016). "HOXD1, HOXD3, and HOXD4 were transcription factors and have been recognized as oncogenes in many cancers, such as liver cancer, gastric cancer, breast cancer, and as an inhibitor in kidney renal clear cell carcinoma." (PMID 37827698, 2023). "By analyzing the mRNA microarrays from TCGA, we determined that LATS1/2 level was positively correlated with STARD13, CDH5, HOXD1, and HOXD10 levels in breast cancer tissues, respectively." (PMID 29848346, 2018). "Here, we identify CDH5, HOXD1, and HOXD10 as putative STARD13 ceRNAs and they display concordant patterns with STARD13 in different metastatic potential breast cancer cell lines and tissues." (PMID 26985770, 2016). "Despite multiple relationships, our study provide solid evidences to outline the novel roles of STARD13-, CDH5-, HOXD1-, and HOXD10-3’UTRs in modulating breast cancer metastasis via competing for miR-9, miR-10b and miR-125b in vitro and in vivo." (PMID 26985770, 2016). "To investigate whether STARD13-correlated ceRNA network is involved in breast CSC formation, we first detected the expression levels of STARD13, CDH5, HOXD1, and HOXD10 in a pool of CSCs naturally arising within breast cancer cells." (PMID 29848346, 2018). "In sum, these data testify our hypothesis that STARD13, CDH5, HOXD1, and HOXD10 may bind with miR-9, miR-10b and miR-125b to suppress breast cancer metastasis." (PMID 26985770, 2016). "This promotes us to explore the functions of STARD13-, CDH5-, HOXD1-, and HOXD10-3’UTRs in breast cancer metastasis and whether they possess the functions through acting as ceRNAs." (PMID 26985770, 2016). "Our recent work has confirmed that STARD13, CDH5, HOXD1, and HOXD10 could co-regulate each other through competing for several shared miRNA binding sites, and thus formed a ceRNA network to coordinately inhibit breast cancer EMT and metastasis, which is denoted as STARD13-correlated ceRNA network." (PMID 29848346, 2018). "Given the crucial role of STARD13-, CDH5-, HOXD1-, and HOXD10-3’UTRs in breast cancer metastasis, we believe that STARD13-, CDH5-, HOXD1-, and HOXD10-3’UTRs could be therapeutic targets for the development of anti-metastatic strategy for breast cancer treatment in the near future." (PMID 26985770, 2016).
glioma (3 papers, 2015 to 2023). A benign or malignant brain and spinal cord tumor that arises from glial cells (astrocytes, oligodendrocytes, ependymal cells). "Analysis of HOXD gene expression in human low-grade gliomas tissues revealed that HOXD1 and HOXD12 were highly expressed in gliomas, whereas the expression of HOXD3 was depressed." (PMID 29383189, 2017). "The upregulation of HOXA9, HOXC6, HOXC11, HOXD1, and HOXD8 expression is associated with the proliferation and growth of glioma." (PMID 26565624, 2015). "Another research examined the expression of HOXD family genes by QPCR in 14 pediatric low-grade gliomas and found that HOXD1 and HOXD12 were overexpressed in tumor tissue compared to non-neoplastic tissues, while HOXD3 presented lower expression in grade I glioma." (PMID 37547473, 2023).
gastric cancer (2 papers, 2022 to 2023). A primary or metastatic malignant neoplasm involving the stomach. "In addition, methylated HOXD1 is selected as a marker of lymph node metastasis in gastric cancer." (PMID 36447287, 2022).
neuroblastoma (2 papers, 2012 to 2018). Neuroblastoma (NB) is the most common solid, extracranial childhood tumor. "In neuroblastoma, however, the HOX genes have been linked to differentiating cells and specifically HOXD1 identified here (as well as HOXC6 and HOXD8) are associated with differentiation towards a neuronal phenotype." (PMID 29757368, 2018). "Previous studies have revealed a marked induction of HOXD1 and HOXD8 following RA treatment in several human neuroblastoma cell lines examined including SK-N-BE, CHP-134, SK-N-SH, LA-N-1 and LA-N-5." (PMID 22879880, 2012).
ovarian carcinoma (2 papers, 2014 to 2017). A malignant neoplasm originating from the surface ovarian epithelium. "HOXD1, which is also adjacent to HOXD-AS1, has been linked with locus rs2072590 associated with an increased risk of ovarian cancer, more significantly for the serous subtype." (PMID 25522241, 2014).
anencephaly (1 paper, 2019). A rare neural tube defect during pregnancy, resulting in the absence of a large portion of the brain and skull in the fetus. "In conclusion, these data identify the abnormal upregulation of HOX genes, especially HOXB4, HOXC4 and HOXD1, concomitant with decreased H3K27me3 levels in human anencephaly cases." (PMID 31856916, 2019).
autism (1 paper, 2025). Persistent deficits in social interaction and communication and interaction as well as a markedly restricted repertoire of activity and interest as well as repetitive patterns of behavior. "HOX genes (HOXD1) map into human chromosome 2 region (2q31–2q33), where GAD1 and DLX2 also reside, and while linkage to autism is weak for the genes in this region (e.g., GAD1), the sheer proximity could potentially signify transcriptional coregulation." (PMID 39758604, 2025).
bladder urothelial carcinoma (1 paper, 2023). "Meanwhile, the association of HOXD1 expression with DFI was analyzed, and the results showed that high expression of HOXD1 induced poor DFI in KICH and PRAD (p < 0.01); HOXD3 in ACC, BLCA (bladder urothelial carcinoma), and PRAD (p < 0.01); HOXD4 in BLCA, ESCA, KICH, PCPG, and PRAD (p < 0.01)." (PMID 37827698, 2023).
Breast invasive carcinoma (1 paper, 2023). "However, the HOXD1 expression was decreased in BRCA (Breast invasive carcinoma), COAD (colon adenocarcinoma), KICH (Kidney chromophobe), KIRC, KIRP (Kidney renal papillary cell carcinoma), READ (Rectum adenocarcinoma), and TGCT (Testicular germ cell tumors) (p < 0.01)." (PMID 37827698, 2023).
colon cancer (1 paper, 2013). "Hoxd1 has previously been reported to be hypermethylated in a colon cancer cell line and HOX gene clusters in human lung carcinomas and in noncancerous lung tissues." (PMID 24204690, 2013).
lymph node metastasis (1 paper, 2017). "Finally, 12 probes were chosen for the final classification and associated with 14 genes including several lymph node metastasis-related genes, such as HOXD1, NMT1, and SEMA3E." (PMID 28951630, 2017).
Parkinson disease (1 paper, 2022). A progressive degenerative disorder of the central nervous system characterized by loss of dopamine producing neurons in the substantia nigra and the presence of Lewy bodies in the substantia nigra and locus coeruleus. "Interestingly, pathway enrichment analysis of RNA-seq data of HtrA1 Tg mice showed two significant enriched pathways, ~ HOXD1 and Parkinson’s disease, that are evidently related to angiogenesis as discussed." (PMID 36142120, 2022).
renal carcinoma (1 paper, 2025). A carcinoma arising from the epithelium of the renal parenchyma or the renal pelvis. "TGF-β has been implicated in EMT in renal cancer, thus suggesting that HOXD1 functions as a tumor suppressor via inhibition of TGF-β." (PMID 39858044, 2025).
tumor (8 papers, 2013 to 2023). "Meantime, the analysis of HOXD1 expression in TCGA databases revealed the downregulation of this gene in tumor tissues from BRCA, COAD, KICH, KIRC, KIRP, READ, and TGCT." (PMID 37827698, 2023). "Our first pan-cancer analyses of HOXD1, HOXD3, and HOXD4 indicate that those factors were differentially expressed between normal and tumor tissues and reveal associations of gene expression with clinical indicators." (PMID 37827698, 2023). "In the research of tumor progression and migration, the expression of HOXD1 is involved in cell proliferation, cell cycle, and the TGF-β signaling in KIRC." (PMID 37827698, 2023). "In this case, we found 12 HOX genes with significantly different (BH p < 0.05) expression in GBM compared to normal tissue, 11 genes up-regulated in tumour and HOXD1 down-regulated." (PMID 35418059, 2022). "The lncRNA insulin-like growth factor 2 antisense RNA (IGF2-AS) is predicted to exert a tumor suppressive effect by HOXD1." (PMID 36213580, 2022). "In mice fed with WD, proximal colon mucosa, the predominant site of cancer formation in LS, exhibited a significant expression decrease in tumor suppressor genes, Dkk1, Hoxd1, Slc5a8, and Socs1, the latter two only in the Mlh1+/- mice." (PMID 24204690, 2013). "Four out of six neoplasias were found in the mice showing higher methylation at CGIs of all five genes Dkk1, Slc5a8, Hoxd1, Socs1 and Sfrp1 (B219, B220), of the four genes Dkk1, Hoxd1, Socs1 and Sfrp1 (B215), or of Dkk1 (B236)." (PMID 24204690, 2013). "Compared with the normal tissues, most of the HOX genes showed increased expression in tumor tissues, only HOXB1 and HOXD1 decreased expression in PGs samples, and the difference in expression of these HFGs in normal and tumor tissues was statistically significant except HOXB8 and HOXC12." (PMID 37547473, 2023). "Furthermore, in the KIRC, all HOXD1, HOXD3, and HOXD4 expressions were negatively linked with the tumor stage." (PMID 37827698, 2023). "The expression levels of HOXD1/3/4/8/9/10 correlated with tumor stage." (PMID 36213580, 2022). "Besides, we observe lower methylation levels of HOXC10 than HOXD1 on both tumor and normal samples in TCGA dataset, which is also revealed by the sequencing results that fewer methylation events occur on both tumor and normal samples for HOXC10 than HOXD1." (PMID 36447287, 2022). "In varying degrees, HOXD1, HOXD3, and HOXD4 participated in the initiation and progression of the tumor." (PMID 37827698, 2023). "HOXD1, HOXD3, and HOXD4 are members of the HOXD genes family and are related to tumorigenesis of the tumor." (PMID 37827698, 2023). "NDRG2 is a relevant biomarker for predicting aggressive behavior, tumor recurrence and overall patient survival, independently or in combination with other factors, such as CD24, phospho-STAT3, and HOXD1." (PMID 26506239, 2016). "Tumor Immune Estimation Resource, Single-Cell Analysis, and gene set enrichment analysis (GSEA) were performed to investigate the special functions and mechanisms of the HOXD1, HOXD3, and HOXD4 in cancers." (PMID 37827698, 2023). "Therefore, In the KIRC, all of HOXD1, HOXD3, and HOXD4 expression was significantly correlated with tumor stage (shown in red square frame)." (PMID 37827698, 2023). "HOXD1 was lowly expressed in KIRC and correlates with patient OS, DFS, and advanced tumor stage." (PMID 36213580, 2022). "NDRG2 may be a tumor biomarker, and the combination of NDRG2 with other molecules, such as CD24 and HOXD1, may yield more specific or sensitive biomarkers." (PMID 26506239, 2016). "Moreover, HOXD1, HOXD3, and HOXD4 could be applied to evaluate immune cells’ infiltration in various tumor tissues." (PMID 37827698, 2023).
cancer (7 papers, 2013 to 2025). A tumor composed of atypical neoplastic, often pleomorphic cells that invade other tissues. "Other than that, this transcription factors also plays an important role in cancer metastasis by influencing the expression of miRNAs that cause effects on HOXD1 downstream target genes, such as Rhoc, which plays critical role in cytoskeletal reorganization and cancer metastasis." (PMID 31315241, 2019). "GSEA was performed to assess the signaling pathways of HOXD1, HOXD3, and HOXD4 that cause their differential expression in each cancer." (PMID 37827698, 2023). "Above all, these results indicated that HOXD1, HOXD3, and HOXD4 expression was significantly enriched with pathways associated with the immune-activation status and progression of cancers." (PMID 37827698, 2023). "Many homeobox genes are found hypermethylated in different cancer types, including HOXD1 and HOXD10 that are also identified in this study." (PMID 36447287, 2022). "These genes related to the selected probes are mostly associated with cancer and LN metastasis, such as TP73, PDX1, FUT8, HOXD1, NMT1, and SEMA3E." (PMID 28951630, 2017). "On the contrary, there are also some genes, such as HOXB3, HOXD1, HOXC9, and HOXA13, that are highly expressed in some cancers and have better OS (p<0.05)." (PMID 39980564, 2025). "Results confirmed that differential expression of HOXD1, HOXD3, and HOXD4 between cancer tissues and normal tissues existed in many types of cancer." (PMID 37827698, 2023). "The current study conducted the bioinformatics database to analyze the expression of HOXD1, HOXD3, and HOXD4 in common cancers." (PMID 37827698, 2023). "Meantime, the GSEA result showed that HOXD1, HOXD3, and HOXD4 were connected with the immune infiltration in pan-cancer." (PMID 37827698, 2023). "Meantime, HOXD1, HOXD3, and HOXD4 co-inhibition was demonstrated in 7 cancers, such as BRCA, COAD, KICH, KIRC, KIRP, READ, TGCT." (PMID 37827698, 2023). "The involvement of HOXD10, HOXD11, HOXD1, HOXC4, HOXC10, and HOXA11, in the cell cycle and the EMT, confirm their role in the cancer-related signaling pathways." (PMID 35562533, 2022). "The feature selection procedure extracted several cancer-related and lymph node metastasis-related genes, such as TP73, PDX1, FUT8, HOXD1, NMT1, and SEMA3E." (PMID 28951630, 2017). "Whereas, the molecular function of HOXD1, HOXD3, and HOXD4 in tumorigenesis, recurrence, and metastasis of various cancers have still unknown." (PMID 37827698, 2023). "The outcomes showed that HOXD1 was positively connected with the infiltration levels of B cells, CAF, Endo, macrophages, monocytes, neutrophils, dendritic cells, and Tregs in most of the cancers." (PMID 37827698, 2023). "Furthermore, the expression of HOXD1, HOXD3, and HOXD4 remarkably correlated with histological grade was demonstrated in 11 cancer types." (PMID 37827698, 2023). "Our findings suggest that HOXD1, HOXD3, and HOXD4 expression will bring different prognostic outcomes, which needs to be further studied for the specific role of HOXD1, HOXD3, and HOXD4 in each cancer." (PMID 37827698, 2023). "Analysis of DEHGs in oncogenic pathways using GSCALite26 indicated that HOXD10, HOXD11, HOXD1, HOXC4, HOXC10, and HOXA11 may have a crucial role in the activation of epithelial-mesenchymal transition (EMT) in cancer, represented in the form of heatmap percentage." (PMID 35562533, 2022).
infection (1 paper, 2018). The state of being infected such as from the introduction of a foreign agent such as serum, vaccine, antigenic substance or organism. "(A) Lentiviral infection efficiency of MDA-MB-231 cells stably expressing STARD13-3′UTR, CDH5-3′UTR, HOXD1-3′UTR, and HOXD10-3′UTR was examined by qRT-PCR." (PMID 29848346, 2018). "(B) Lentiviral infection efficiency of MCF-7 cells stably depleted of STARD13, CDH5, HOXD1, and HOXD10 was verified by Western blot analysis." (PMID 29848346, 2018).
HOXD1 also shares sentences with these, for which no sentence is quoted: colon adenocarcinoma (1 paper); glioblastoma (1); Kidney chromophobe (1); liver cancer (1); lung carcinoma (1); oligodendroglioma (1); rectum adenocarcinoma (1); renal cell carcinoma (1); testicular germ cell tumor (1).